WNT11 (Wnt family member 11)
Description:
Ligand for members of the frizzled family of seven transmembrane receptors. Probable developmental protein. May be a signaling molecule which affects the development of discrete regions of tissues. Is likely to signal over only few cell diameters.
Synonyms: HWNT11
Tractability: Antibody: its Gene Ontology location is reachable by antibodies, with high confidence; UniProt places it where antibodies can reach, with medium confidence; UniProt predicts a signal peptide or a membrane-spanning region.
Gene: Protein-coding gene on chromosome 11 (76,186,325 to 76,210,761, reverse strand). Ensembl gene ENSG00000085741.
Subcellular location: Secreted, extracellular space, extracellular matrix
Pathways (Reactome):
Signal Transduction: Ca2+ pathway; Class B/2 (Secretin family receptors); PCP/CE pathway; WNT ligand biogenesis and trafficking
Developmental Biology: Formation of the ureteric bud
Gene Ontology:
Molecular function: protein binding; protein kinase activator activity; cytokine activity; frizzled binding; signaling receptor binding
Biological process: adrenal gland development; cloacal septation; embryonic skeletal system development; intracellular signal transduction; lung-associated mesenchyme development; mesonephric duct development; negative regulation of canonical Wnt signaling pathway; neuroendocrine cell differentiation; positive regulation of DNA-templated transcription; secondary palate development; signal transduction; ureteric bud morphogenesis; canonical Wnt signaling pathway; cell fate commitment; cellular response to retinoic acid; negative regulation of cartilage development; neuron differentiation; Wnt signaling pathway, calcium modulating pathway; Wnt signaling pathway, planar cell polarity pathway; atrial septum development; cell differentiation; primary heart field specification; response to nutrient levels; secondary heart field specification; ventricular septum development; and 1 more
Cellular component: cytoplasm; extracellular region; extracellular matrix
Genetic constraint (gnomAD): Loss-of-function variants: 20 observed, 29.26 expected, observed/expected ratio (o/e) 0.68, 90% interval 0.48 to 0.99. The upper end of that interval is the gene's LOEUF score, 0.99, which puts it in group 4 of 6, group 1 being the genes least tolerant of losing a copy. Missense variants: 459 observed, 472.01 expected, observed/expected ratio (o/e) 0.97, 90% interval 0.9 to 1.05. Synonymous variants: 200 observed, 194.95 expected, observed/expected ratio (o/e) 1.03, 90% interval 0.91 to 1.15.
Homologues: Orthologues: chimpanzee WNT11 (100% identical), dog WNT11 (99% identical), pig WNT11 (99% identical), guinea pig WNT11 (98% identical), rabbit WNT11 (98% identical), mouse Wnt11 (97% identical), rat Wnt11 (97% identical), macaque WNT11 (94% identical), tropical clawed frog wnt11 (79% identical), zebrafish wnt11 (75% identical), Drosophila melanogaster Wnt5 (36% identical), Caenorhabditis elegans cwn-2 (34% identical), and 4 more. Paralogues in human: WNT4 (40% identical), WNT2B (38% identical), WNT5B (38% identical), WNT5A (38% identical), WNT10A (37% identical), WNT2 (37% identical), WNT3 (36% identical), WNT7A (36% identical), WNT7B (36% identical), WNT10B (36% identical), WNT16 (36% identical), WNT3A (36% identical), and 6 more.
Diseases named in the same sentence as WNT11 in open-access papers:
WNT11 is named in the same sentence as 105 diseases in open-access papers, as found by Europe PMC text mining. Sharing a sentence is not in itself a finding about the gene and the disease. The quoted sentences say what the papers report.
breast carcinoma (43 papers, 2008 to 2025). "In colorectal cancer (CRC), pancreatic ductal adenocarcinoma (PDAC), and breast cancer—the major sources of LM—WNT11 has been associated with epithelial–mesenchymal transition (EMT), matrix remodeling, and stromal reprogramming." (PMID 41426343, 2025). "Exosome activity is associated with the Wnt11 produced in breast cancer cells, and exosomes secreted from fibroblast are internalized by BCCs and further loaded with Wnt11." (PMID 36901813, 2023). "Previous studies have shown that upregulation of Wnt11 increases the migratory capacity of breast cancer cells and upregulating the Wnt signaling pathway is associated with trastuzumab-resistant breast cancers." (PMID 35954313, 2022). "Aberrant Wnt signalling is a hallmark for many cancers and upregulated Wnt-11 expression is reported in breast cancer." (PMID 35884609, 2022). "Taken together, our study revealed a novel auto-stimulatory loop in which ROR2 triggers the expression of its own ligand, WNT11, resulting in enhanced tumor invasion associated with breast cancer metastasis." (PMID 34911552, 2021). "In short, although the mechanism underlying Wnt11 expression differs between studies, it is clear that induction of Wnt11 expression results in (pro)metastatic behavior of breast cancer cells." (PMID 25713299, 2015). "More recently, it has been demonstrated that Wnt11-loaded exosomes excreted by tumor-associated fibroblasts can activate the planar cell polarity signaling pathway and, through this mechanism, induce breast cancer metastasis." (PMID 25713299, 2015). "Luga and colleagues have shown that exosomes produced by stromal cells are taken up by breast cancer cells and are then loaded with Wnt11, which is associated with stimulation of the invasiveness and metastasis of the breast cancer cells." (PMID 26156517, 2015). "In summary, these results confirm the validity of Wnt11 as a genuine Kaiso target in mILC and demonstrate its regulation in E-cadherin-deficient breast cancer cells by nuclear p120." (PMID 25713299, 2015). "Furthermore, overexpression of WNT-11 has been associated with migration and metastasis of breast cancer cells." (PMID 35198956, 2022). "Moreover, WNT11 was recently identified as one of three WNT genes mutated specifically in breast cancer metastases compared with matched primary tumors." (PMID 34911552, 2021). "In a prior study in cancer cells, we showed that exosomes from fibroblasts acquire Wnt11 when internalized by breast cancer cells to activate autocrine Wnt-PCP signaling and promote cell motility and formation of protrusions." (PMID 39791757, 2025). "In mouse breast cancer cell lines, knockdown of Wnt11 reduced cell motility and protrusive activity." (PMID 36982422, 2023). "In breast cancer, CD81+ exosomes released by fibroblasts have been implicated in promoting the migration of breast cancer cells through the interaction of CD81 and Wnt11." (PMID 38136327, 2023). "WNT11 was also shown to mediate WNT/PCP signaling via the RHO/ROCK pathway affecting the aggressive phenotype of breast cancer cells." (PMID 35668332, 2022). "Wnt-11 mRNA expression in both breast cancer cell lines were quantified after growing cells on 3D PHA scaffolds on Day 0 using qRT-PCR." (PMID 35884609, 2022). "Kaiso target gene Wnt11 induces anoikis resistance of metastasis in mouse lobular breast cancer cells." (PMID 33902604, 2021). "Although the results did not quite reach significance due to the limited number of patient samples, the results do indicate that WNT11/ROR2 exerts an unfavorable role in brain metastasis of breast cancer patients in vivo." (PMID 34911552, 2021). "WNT11 was reported to be highly amplified in 6.2% of breast cancer patients and observed in specific tumor cell subpopulations." (PMID 34911552, 2021).
breast carcinoma (continued). "Taken together, we show for the first time that ROR2 can trigger an autocrine, invasion-promoting signaling response via RHO/ROCK by inducing expression of its own ligand, WNT11, in human breast cancer." (PMID 34911552, 2021). "Taken together, these results imply that WNT11 is able to activate tumor-promoting signaling pathways in breast cancer cells via its interaction with ROR2." (PMID 34911552, 2021). "On the one hand, Wnt11, as a tumour promoter, is involved in the proliferation, migration and invasion of various cancers, such as breast cancer, colon cancer, prostate cancer and leukaemia." (PMID 33417298, 2021). "CD81+ CAF-derived exosomes promote breast cancer cell protrusions and motility, and tumor metastasis in vivo; breast cancer cell produced Wnt11 interacts with exosomes received from CAFs to activate PCP signaling." (PMID 32957712, 2020). "b mRNA expression of WNT3A, WNT3, WNT5A, WNT5B, and WNT11 in five different breast cancer subtypes based on bc-GenExMiner v4.1 according to the Sørlie’s subtypes (****p < 0.0001; Red star: the former > the latter; Green Star: the former < the latter)." (PMID 31462314, 2019). "Prognostic value of WNT3 d and WNT11 e mRNA levels in human breast cancer, data obtained from the KM-plotter." (PMID 31462314, 2019). "We observed an upregulation of Wnt11 that previously has been shown to increase cell proliferation, migration and invasion in breast cancer." (PMID 30602372, 2019). "Overexpression of WNT11 in EMSCs and BT-474 breast cancer cell lines resulted in higher MMP-2 and/or MMP-9 zymographic activities." (PMID 26861754, 2016). "Subsequent anchorage-independent expression of the Kaiso target gene Wnt11 drives anoikis resistance of metastatic breast cancer cells through activation of the Rho-Rock signaling pathway." (PMID 25713299, 2015). "Recently, Wnt11-induced Wnt signaling has been identified as a major paracrine factor driving breast cancer invasion." (PMID 25713299, 2015). "The differential drug sensitivity of WNT2, WNT7B, and WNT11 suggests that these genes may serve as predictive biomarkers for therapeutic responses in breast cancer." (PMID 41044153, 2025). "The positive correlation between WNT11 and Simvastatin, and fluvastatin suggests that these lipophilic statins may play a role in targeting WNT11-driven breast cancer." (PMID 41044153, 2025). "Mechanistically, it could be shown that Wnt11 is loaded onto fibroblast-derived exosomes by breast cancer cells and is then secreted in an autocrine manner to activate Wnt/PCP signaling via Fzd6." (PMID 36982422, 2023). "WNT5B has been shown to interact with ROR2 in osteosarcoma, while preliminary results indicate that WNT11 could be a ligand of ROR2 in breast cancer." (PMID 35246138, 2022). "Moreover, it has been established that Wnt-11 expression triggers oestrogen receptor alpha and modulates cellular migration in breast cancer." (PMID 35884609, 2022). "This might reflect hormone regulation of WNT11 expression, as WNT11 is downregulated by dihydrotestosterone in prostate cancer and upregulated by estrogen in breast cancer." (PMID 31261741, 2019). "Moreover, in subsequent studies, the authors showed that, when taken up by breast cancer cells, fibroblast-derived exosomes co-localize with breast cancer cell-derived Wnt11 within endocytic vesicular structures." (PMID 27515302, 2016). "Interestingly, the WNT11 locus maps to 11q13, a region frequently found amplified in human breast cancer." (PMID 25713299, 2015). "In addition, estrogen related receptor α (ERRα)- and β-catenin-dependent Wnt11 expression has been shown to act as an autocrine promigratory cue in breast cancer cell lines." (PMID 25713299, 2015). "Interestingly, several lines of research have indicated that Wnt11-mediated signaling acts as a player in breast cancer progression." (PMID 25713299, 2015).
breast carcinoma (continued). "Furthermore, it remains to be established if other proteins e.g. Wnt11 or bcl homologues potentiate the tumour suppressor role of BCL2 in breast cancer." (PMID 18510726, 2008). "Indeed, Luga and colleagues demonstrated that EVs released from cancer-associated fibroblasts (CAFs) promote the increased motility and metastatic capability of breast cancer cells, which is dependent on the interaction of breast cancer cell-produced Wnt11 and CAF-derived CD81." (PMID 37760975, 2023). "WNT11 mRNA overexpression was associated with poor prognosis in a subset of patients with AML, and thus WNT11 may have an antiapoptotic function in Tim-3+ blasts in prostate and breast cancer." (PMID 29179486, 2017). "In addition, a recent study found that fibroblast-induced exosomes could mobilize Wnt11 from breast cancer cells to induce planar cell polarity signalling." (PMID 25968605, 2015). "In addition, cell-based assays have demonstrated that Wnt-11 promotes cardiac differentiation, increases proliferation, migration and transformation of intestinal epithelial cells, reduces apoptosis in breast cancer cells and increases cell viability in chinese hamster ovary (CHO) cells." (PMID 20219091, 2010). "The mRNA expression of PCP-related genes VANGL2, NOS1AP, SCRIB, WNT11 and SMURF2 in VANGL2- or NOS1AP-amplified breast cancers (most cases are co-amplified) is heterogeneous in molecular sub-types." (PMID 36675340, 2023). "Our data confirmed that PHA-based 3D scaffolds allowed for breast cancer cells to grow in 3D, and the EMT/Wnt11 gene expressions increased significantly as shown by others in Matrigel-based 3D cultures." (PMID 35884609, 2022). "WNT11 binds to the CRD of ROR2 and mediates WNT/PCP signaling via the RHO/ROCK pathway that confers an aggressive phenotype to breast cancer cells." (PMID 34911552, 2021). "Our data shows that two of the Wnt/PCP genes (WNT11 and VANGL2) are targets of miR-1291 and both have been reported to promote cell motility and metastasis in breast cancer." (PMID 33343622, 2020). "Wnt-11 has previously been shown to be important for the survival and/or viability of MCF-7 breast cancer cells and CHO cells, suggesting that this is a general role for Wnt-11." (PMID 20219091, 2010). "The highest frequency rate of “amplification” of WNT2, WNT7B, and WNT11 was recorded at 3.69%, 15.83%, and 33.25%, respectively, notably within The Metastatic Breast Cancer Project (Provisional, December 2021)." (PMID 41044153, 2025). "Two other genes involved in PCP, ligand WNT11 and ubiquitin ligase SMURF2, are amplified in smaller percentages of breast cancer cases (WNT11: in 5.2% of cases in TCGA and 6.7% of cases in METABRIC; SMURF2: in 6.2% of cases in TCGA and 8.1% of cases in METABRIC)." (PMID 36675340, 2023). "The breast cancer pathway was further activated through the FGF18, HEYL, and WNT11 genes." (PMID 37887323, 2023). "It has been reported that triple-negative breast cancer, which is an aggressive subtype of breast cancer, and expresses high levels of Wnt-11, which is accepted as a cancer stem cell (CSC)-like marker." (PMID 35884609, 2022). "To test whether the induction of WNT11 is specific for MCF-7 cells or a general phenomenon in breast cancer, we overexpressed ROR2 in different human breast cancer cell lines." (PMID 34911552, 2021). "Wnt11 aids cell migration and metastasis in breast cancer cells, and the sorting of the Wnt11 cargo to EVs is supported by CD81, but not other tetraspanins." (PMID 33669943, 2021). "Wnt ligands, such as WNT3A, WNT9A, WNT11 and WNT5B were highly amplified in breast cancers." (PMID 31462314, 2019). "For instance, in breast cancer, WNT11 was shown to bind the non-canonical receptor ROR2." (PMID 36982422, 2023).
breast carcinoma (continued). "Most importantly, 5 genes were found to be associated with all of the most highly enriched GO terms and KEGG pathways: WNT5A, WNT6, WNT11, WNT5B and LAMA1, which suggested that WNTs may be essential targets of ATBF1 and may contribute to breast cancer tumorigenesis." (PMID 36476423, 2022). "Although there is a strong association between Wnt11 gene expression and hormone-independent growth of prostate cancer cells, its role in breast cancer may not be through Wnt11-mediated tumor cell proliferation but rather inhibition of apoptosis." (PMID 24324894, 2013).
prostate carcinoma (20 papers, 2010 to 2025). A carcinoma that arises from epithelial cells of the prostate gland. "Among these, signals mediated by Wnt-11, which control cell movement in the embryo, are implicated in breast, colorectal, and prostate cancer cell migration and invasion." (PMID 31261741, 2019). "FZD8 is directly targeted and activated by ERG, which is involved in bone metastasis of prostate cancer by regulating Wnt-11 and TGF-β signaling to stimulate epithelial–mesenchymal transition in prostate cancer." (PMID 36579559, 2022). "Wnt5a promotes liver fibrosis by FZD2 and FZD8 42, and Wnt11 binds to FZD8 known to be involved in TGF-β signaling in prostate cancer." (PMID 33391533, 2021). "Wnt-11 also controls expression of a neurone-specific enolase, which drives neuronal differentiation and enhanced cell viability and migration in prostate cancer." (PMID 31718047, 2019). "In order to determine the pattern of expression of Wnt-11 protein in CRC, we used antibodies previously optimized for detection of Wnt-11 in prostate cancer to carry out immunostaining for Wnt-11 in benign and tumor areas of tumor sections from CRC patients." (PMID 31261741, 2019). "Here, we provide evidence that FZD8 is a major Wnt-11 receptor in prostate cancer that integrates Wnt-11 and TGF-β signals to promote EMT." (PMID 29717114, 2018). "Further studies will be needed to determine which Wnt co-receptors are important for Wnt-11 signaling in prostate cancer." (PMID 29717114, 2018). "In contrast, FZD8 was upregulated in prostate tumor datasets, correlated with WNT11 expression in prostate cancer cell lines and FZD8 protein levels correlated with Wnt-11 in prostate TMAs." (PMID 29717114, 2018). "Here the authors show that in prostate cancer cells Wnt11 signals through the Fzd8 receptor and report an interaction between Fzd8 and TGF-β receptors regulating the transcription of a subset of TGF-beta genes." (PMID 29717114, 2018). "Our findings show that FZD8, like Wnt-11, is highly expressed in more aggressive prostate cancer cell lines." (PMID 29717114, 2018). "Canonical Wnt11 promotes neuroendocrine-like differentiation, survival and migration of prostate cancer cells, and is induced by estrogen-related receptor α and β-catenin and acts in an autocrine manner to increase cancer cell migration." (PMID 27329839, 2016). "Wnt-11 promoted prostate cancer cell invasion and migration and it was required for prostate cancer cell survival." (PMID 22325146, 2012). "Elevated expression levels of Wnt1, Wnt5a, Wnt7b, and Wnt11 have also been correlated to prostate cancer aggressiveness." (PMID 24212796, 2011). "Taken together, these observations suggest that Wnt-11 is a potential therapeutic target in the treatment of prostate cancer." (PMID 20219091, 2010). "In contrast, Wnt-11 did not induce NSE expression in RWPE-1 cells, which are derived from benign prostate, suggesting that the role of Wnt-11 in NED is specific to prostate cancer." (PMID 20219091, 2010). "Increased expressions of Wnt ligands, including Wnt-5a and Wnt-11, are shown in primary prostate cancer tissues and bone-metastasis lesions, and elevated Wnt-11 expression is correlated with PSA levels and implicated in neuroendocrine (NE) transdifferentiation." (PMID 38531859, 2024). "Furthermore, we previously reported that Wnt-11 leads to neuroendocrine differentiation in prostate cancer, and Wnt-11 regulates proteins including PKC, JNK, NF-κB, Rho, PKA, and PI3K." (PMID 33557112, 2021). "In addition, we have found that higher Gleason score patients have the highest expression levels of Wnt11 (prostate cancer Gleason Wnt-11 file)." (PMID 32182839, 2020). "Moreover, FZD8 transduces Wnt-11 signals that promote prostate cancer cell migration, invasion and the epithelial mesenchymal transition (EMT)." (PMID 31261741, 2019). "Wnt-11 is required for prostate cancer cell migration and invasion." (PMID 29717114, 2018).